WFS1 (wolframin ER transmembrane glycoprotein)
Diseases named in the same sentence as WFS1 in open-access papers (continued):
Sharing a sentence is not in itself a finding about the gene and the disease.
Hyperglycemia (13 papers, 2012 to 2025). An increased concentration of glucose in the blood. "A number of studies have investigated the association between WFS1 gene polymorphism and insulin secretion, insulinemia, insulin sensitivity, as well as risk of hyperglycemia and T2DM." (PMID 35207731, 2022). "We decided to test his mother, as she presented hyperglycaemia, and the same missense mutation in WFS1 gene was found." (PMID 36294752, 2022). "The post hoc Duncan test revealed that glucose levels were significantly higher at the time point of 30 min in all groups, and Wfs1-deficient mice had augmented hyperglycaemia compared to heterozygotes (p < 0.05) or their wild-type littermates (p < 0.05)." (PMID 27069934, 2016). "Hence, the upregulated Wfs1 in the hypothalamus might be associated with improvement of hyperglycemia in the exercised GK rats." (PMID 31579613, 2019). "By the age of 16 months, 90% of saline-treated Wfs1 KO animals had developed hyperglycemia and needed supportive insulin administration." (PMID 34831417, 2021). "Thereafter, an increasing number of Wfs1-ex5-KO232 rats develop hyperglycaemia between 11–12 months of age." (PMID 28860598, 2017). "Analysis of variants in the family revealed a heterozygous pathogenic variant in the WFS1 gene in the patient’s father, who has isolated hyperglycemia, with no other disorders." (PMID 39766859, 2024). "However, treatment with liraglutide or with liraglutide in combination with 7,8-DHF prevented the development of hyperglycemia in Wfs1 KO rats." (PMID 33500541, 2021). "Furthermore, overexpression of Wfs1 in cells increased ER Ca2+ levels to enhance neuronal responsiveness to hyperglycemia." (PMID 31579613, 2019). "By 13 months of age, all Wfs1-ex5-KO232 male rats in our study displayed fasting hyperglycaemia." (PMID 28860598, 2017). "Thus, glycosuria appears to precede the development of hyperglycaemia in Wfs1-ex5-KO232 rats." (PMID 28860598, 2017). "It is not known whether retinal gliosis is a direct result of WFS1 dysfunction in the retina or is caused by the hyperglycaemia that is seen in older mutant animals." (PMID 28860598, 2017). "As expected, and in agreement with previous studies, older Wfs1 KO rats developed fasting hyperglycemia (p < 0.05) and treatment with 7,8-DHF was not preventing an increase in blood glucose levels." (PMID 33500541, 2021). "At the age of 16 months, most of the Wfs1 KO animals had developed hyperglycemia, therefore it was not ethical to perform IPGTT." (PMID 34831417, 2021). "However, to the best of our knowledge, no mutant Wfs1 mice display fasting hyperglycaemia." (PMID 28860598, 2017).
MODY (13 papers, 2018 to 2025). "The first WFS1 variant shown to cause MODY was reported in a Finnish family before gnomAD but remains absent in 12,562 Finnish individuals in gnomAD." (PMID 40779032, 2025). "Although WFS1 mutations have been associated with MODY, limited studies have explored the relationship between WFS1 mutations and MODY." (PMID 40641032, 2025). "Heterozygous variants in NEUROD1, PDX1, APPL1, and WFS1 have been implicated in MODY, but strong genetic evidence supporting causality is lacking." (PMID 40779032, 2025). "We identified pathogenic/likely pathogenic (P/LP) WFS1 variants in five patients and other P/LP genes linked to MODY, insulin resistance, or lipoatrophic diabetes in seven patients." (PMID 39221226, 2024). "All variants identified, except for WFS1 P320R, were heterozygous, consistent with the dominant inheritance pattern of MODY." (PMID 29439679, 2018). "Consequently, we cannot exclude the possibility that APPL1 or WFS1 harbor extremely rare or low-penetrance MODY-causing variants." (PMID 40779032, 2025). "The first reported MODY-associated variants in NEUROD1, PDX1, APPL1, and WFS1 were <1:20,000 frequency." (PMID 40779032, 2025). "Pathogenic variants were also identified in genes associated with MODY (maturity-onset diabetes of the young), including ABCC8, GCK, KCNJ11, and WFS1." (PMID 40149731, 2025). "The clinical phenotypes caused by WFS1 gene mutations demonstrated heterogeneity across the three families, including manifestations of WS, WFLS, and MODY, as one of these families was identified as having MODY due to a WFS1 mutation." (PMID 40641032, 2025). "We recommend including WFS1 in gene panel tests for MODY to enable the early diagnosis of atypical presentations and clinical benefits for diagnosed patients." (PMID 37277527, 2023). "In all cases, we observed consistent results that APPL1 and WFS1 variants are not enriched in the MODY cohort, whereas NEUROD1 and PDX1 were at a level similar to RFX6." (PMID 40779032, 2025). "Finally, by summarizing the genotype–phenotype relationships of WFS1, it is concluded that the WFS1 gene shows a different association with WS, WFSL and MODY." (PMID 40641032, 2025). "Wide application of sequencing techniques in diverse populations brought to light significant number of heterozygous WFS1 gene mutations contributing to MODY phenotype, although homozygosity is not always exception in MODY incidence." (PMID 37255971, 2023). "Consequently, recent studies identified RFX6 as a novel MODY gene and WFS1, PPARG, and GLIS3 have recently been proposed as potential candidates for these rare MODY forms." (PMID 34079523, 2021). "Heterozygous variants in WFS1 do not appear to be associated with MODY." (PMID 40779032, 2025). "However, our comprehensive analysis of a MODY cohort revealed no significant enrichment of ultra-rare PTVs or damaging missense variants in WFS1." (PMID 40779032, 2025). "Of note, most of the patients with WFS1-DM in our study carried only one pathogenic allele, which may explain the later onset age compared to typical MODY and the lack of typical features of WS1." (PMID 37277527, 2023). "In addition to known MODY genes, we report the identification of variants in RFX6, WFS1, AKT2, NKX6–1 that may contribute to development of MODY." (PMID 29439679, 2018). "In this study, we used a large clinically suspected MODY cohort and population controls to assess the genetic evidence for NEUROD1, PDX1, APPL1, and WFS1." (PMID 40779032, 2025). "Recently, three additional candidate genes (WFS1, RFX6 and PCBD1) for MODY‐like phenotypes were proposed." (PMID 36208030, 2022). "In conclusion, we provide genetic evidence that NEUROD1 and PDX1 cause low penetrance MODY whereas variants in APPL1 and WFS1 do not cause MODY and should not be included in MODY genetic analysis." (PMID 40779032, 2025).
MODY (continued). "In summary, rare heterozygous variants in NEUROD1 and PDX1 are low-penetrance causes of MODY, while those in APPL1 and WFS1 lack robust genetic evidence for causality and should not be included in MODY testing panels." (PMID 40779032, 2025).
Glucose intolerance (11 papers, 2015 to 2024). Glucose intolerance (GI) can be defined as dysglycemia that comprises both prediabetes and diabetes. "For instance, our group has extensively tested Liraglutide (LIRA) in an established loss-of-function rat model of WS (Wfs1 coding exon 5 knock-out, Wfs1KO) to show that treatment can substantially delay the onset of glucose intolerance and loss of vision." (PMID 37900147, 2023). "In mice, WFS1 disruption resulted in increased glucose intolerance and insulin deficiency." (PMID 36980809, 2023). "The variant detected in NET11 individuals, who exhibit glucose intolerance alongside SFN, is known to cause a complete breakdown of the WFS1 protein." (PMID 39000354, 2024). "Both of the tested dual agonists DA-CH5 and DA-JC4, were able to normalize glucose intolerance and glucose-stimulated secretory response in symptomatic 5-month-old Wfs1 KO rats." (PMID 37900147, 2023). "This is particularly relevant given our previous observations that Liraglutide treatment was unable to rescue overt glucose intolerance in older Wfs1 KO rats." (PMID 37900147, 2023). "After feeding for 1 month, Wfs1-KO mice fed with control chow developed more severe glucose intolerance." (PMID 36134655, 2022). "At the age of 7.5 months, saline-treated Wfs1 KO rats had developed glucose intolerance, which was confirmed by an area under the curve analysis (p < 0.0001)." (PMID 34831417, 2021). "At the age of 11.5 months, saline treated Wfs1 KO animals remained glucose intolerant (p < 0.0001) whereas liraglutide treatment was effective against the development of glucose intolerance (p < 0.001)." (PMID 34831417, 2021). "Previously we have shown that a 5-month-preventive treatment with liraglutide, starting before the onset of WS symptoms, protected against the development of glucose intolerance in Wfs1 KO rats." (PMID 34831417, 2021). "Previously we found that a 19-weeks preventive liraglutide treatment protected Wfs1 KO rats against the development of glucose intolerance." (PMID 34831417, 2021). "Liraglutide treatment prevented the development of glucose intolerance in Wfs1 KO animals (p < 0.0001)." (PMID 34831417, 2021). "We took 9-month-old Wfs1 knock-out (KO) animals that already had developed glucose intolerance and treated them with liraglutide for 6 months." (PMID 31673100, 2019). "In the current study, to mimic the relatively late diagnosis of WS in patients we used 9-month-old Wfs1 KO animals that already had developed glucose intolerance." (PMID 31673100, 2019). "Our results indicate that chronic liraglutide treatment prevented the development of glucose intolerance in Wfs1 KO rats." (PMID 29976929, 2018). "In this study, we demonstrated that one-week treatment with liraglutide improved glucose control in 5-month-old Wfs1 KO rats, who had already developed glucose intolerance by that age." (PMID 29976929, 2018). "In our previous studies we have shown that acute treatment with valproic acid normalized glucose intolerance in Wfs1 KO mice." (PMID 29976929, 2018). "The different Wfs1 mutant mice that have currently been created show glucose intolerance and diminished insulin secretion." (PMID 28860598, 2017). "The basal blood glucose levels are similar for both genotypes even at the age of 6 months, while Wfs1 KO animals display glucose intolerance already at the age of 2–3 months." (PMID 26379490, 2015). "WFS1 variants were seen in ITA42 and NET11 individuals; only NET11 had glucose intolerance." (PMID 39000354, 2024). "We showed Wfs1-KO mice developed glucose intolerance at 5–6 weeks old." (PMID 36134655, 2022). "By the age of 7.5 months, all of the saline-treated Wfs1 KO rats developed glucose intolerance." (PMID 34831417, 2021). "Therefore, the aim of the present study was to investigate the effect of chronic treatment with GLP-1 receptor agonist on the progression of glucose intolerance in a Wfs1 mutant rat." (PMID 29976929, 2018).
Glucose intolerance (continued). "Early chronic intervention with the GLP-1 receptor agonist liraglutide starting before the onset of metabolic symptoms prevented the development of glucose intolerance, improved insulin and glucagon secretion control, reduced ER stress and inflammation in Langerhans islets in Wfs1 mutant rats." (PMID 29976929, 2018). "The Wfs1-ex5-KO232 rats display glucose intolerance that is steadily exacerbated with age and is accompanied by a reduction of beta cell mass suggesting that a deficit in insulin release underlies their glucose intolerance." (PMID 28860598, 2017). "By 6 months of age, Wfs1-ex5-KO232 rats displayed significant glucose intolerance." (PMID 28860598, 2017). "Glucose intolerance of Wfs1 KO mice seem to correlate well with the human condition." (PMID 26379490, 2015). "Although glucose tolerance in Wfs1 KO mice was not measured in this study, we can presume that 3 months old Wfs1 KO mice used in this study display glucose intolerance that reflect a lack of Wfs1 function." (PMID 26379490, 2015).
Obesity (11 papers, 2014 to 2025). Accumulation of substantial excess body fat. "Collectively, these observations indicate that HFD‐induced obesity and depressive‐like behavior are exacerbated by Wfs1 deficiency." (PMID 39258564, 2024). "The body weight gain of CKO‐normal diet (ND) mice from 6 to 30 weeks was much lower than that of WT‐ND, but the body weight gain of CKO‐HFD mice was higher than WT‐HFD suggesting that Wfs1 deficiency increased the susceptibility to HFD‐inducing obesity." (PMID 39258564, 2024). "WFS1 deficiency in the nervous system exacerbates HFD‐induced obesity and depressive‐like behaviors." (PMID 39258564, 2024). "In this study, the WFS1 rs1046322 and rs9457 were assessed for association with obesity in the ethnic populations of Arabs, South Asians and Southeast Asians." (PMID 37859980, 2023). "Examples of T2DM risk genetic loci, which are also associated with rare recessive disorders, are LIPC (Hepatic lipase deficiency), PDX1 (Pancreatic agedness 1), ENPP1 (Hypophosphatemic rickets, also associated with obesity), WFS1 (Wolfram syndrome 1), and SLC2A2 (Fanconi-Bickel syndrome)." (PMID 30761081, 2019). "For example, it can evaluate the effects of WFS1 gene editing on apoptosis and neural function in brain organoids, providing essential data for optimizing gene therapy strategies in obesity." (PMID 41359105, 2025). "However, whether WFS1 deficiency regulates obesity remains unclear in the nervous system." (PMID 39258564, 2024). "In conclusion, the findings of the present study suggest an ethnic-specific role for WFS1 in obesity." (PMID 37859980, 2023). "In conclusion, only five of the 37 genetic variants previously linked to T2DM and obesity in the Saudi Arabian population [HNF4A-rs4812829, WFS1-rs1801214, DUSP9-rs5945326, ZFAND6-rs11634397, FTO-rs11642841] were associated with prediabetes susceptibility." (PMID 36980809, 2023). "The association tests for the variant and obesity markers showed that obesity traits were significantly associated with the WFS1 rs1046322 variant only in the SEA subpopulation, and not in the Arab or South Asian populations." (PMID 37859980, 2023). "There is a lack of literature reports on associations between WFS1 and obesity." (PMID 37859980, 2023).
bipolar disorder (9 papers, 2009 to 2025). A disorder of the brain that causes unusual shifts in mood, energy, activity levels and the ability to carry out day-to-day tasks. "We propose that mutations in WFS1 predict an increased risk of bipolar disorder and schizophrenia." (PMID 34746052, 2021). "Among these were BDNF, VGF, WFS1, DUSP6, CRHBP, MAOA, and RELN, which have previously been implicated in bipolar disorder." (PMID 31114610, 2019). "Nevertheless, a recent meta-analysis of genome-wide expression studies revealed WFS1 mRNA to be significantly elevated in the prefrontal cortex of patients with bipolar disorder." (PMID 26379490, 2015). "There are conflicting reports on the connection between the WFS1 gene and bipolar disorder." (PMID 24799886, 2014). "Our data raise the possibility that the therapeutic effects of valproate in bipolar disorder may be mediated by the modulation of ER stress through the regulation of WFS1 and GRP94." (PMID 19125190, 2009). "The modulation of ER stress through the activation of WFS1 may be part of valproate's action in bipolar disorder." (PMID 19125190, 2009).
congenital cataracts (9 papers, 2017 to 2025). "In this study, we observed that the heterozygous mutations of PAX6 (c.220A>T/p.Ser74Cys) and WFS1 (c.2070_2079del/p.Cys690TrpfsTer17) were associated with more severe congenital cataracts than the monogenic heterozygous mutation of PAX6 (c.220A>T/p.Ser74Cys) in a Chinese family." (PMID 36843716, 2023). "Further mechanistic investigations are warranted to reveal the interplay between PAX6 and WFS1 in the pathogenesis of congenital cataracts." (PMID 36843716, 2023). "A heterozygote mutation, CRYGD c.70C>A (p.P24T), was identified as cosegregating with congenital cataracts, while another heterozygous mutation, WFS1 c.1514G>C (p.C505S), which had not been reported previously, cosegregated with congenital iris coloboma." (PMID 32148946, 2020).
insulinoma (9 papers, 2015 to 2024). "Another good example is that using of the calpain inhibitor, ibudilast, reversed the effect of WFS1 mutation and normalised the function of rat insulinoma cells." (PMID 37759745, 2023). "In the context of rat insulinoma cells, deficient for Wfs1, ibudilast, a canonical PDE4 inhibitor and NCS1 binding drug, has been used as an efficient treatment to restore calcium homeostasis, cell viability, and glucose-stimulated insulin secretion." (PMID 36320410, 2022). "WFS1 encodes wolframin, a transmembrane protein that localizes primarily in endoplasmic reticulum (ER) membranes and is ubiquitously expressed at the highest levels in the brain, pancreas, heart, and insulinoma beta-cell lines." (PMID 31850070, 2019). "For example, in a mouse insulinoma cell and in the stem cells of individuals both having mutant Wfs1 gene, administration of 4-PBA decreased the levels of UPR components and suppressed the ER stress and increased the insulin content in these cells." (PMID 36725880, 2023). "A study corroborated our results in different species and cell types, namely rat insulinoma, where Wfs1 has been knocked out." (PMID 36320410, 2022). "It has been reported that knockdown of WFS1 induced upregulation of ATF6α and its target genes in the rat insulinoma cells." (PMID 36527091, 2022). "Although the WFS1 gene is abundant, high expression level was detected in pancreatic islets and in insulinoma β-cell lines." (PMID 26426397, 2015). "Similarly, evoked calcium increase is also diminished in fibroblasts of WS1 patients and MIN6 insulinoma cells with WFS1 knocked down." (PMID 37399203, 2023).
autosomal dominant deafness (8 papers, 2017 to 2025). "Mutations in WFS1 are known to cause autosomal dominant deafness (MIM 600965)." (PMID 29258540, 2017).
mood disorder (8 papers, 2013 to 2024). A cognitive disorder a disturbance in which the person's mood is hypothesized to be the main underlying feature. "Initial studies have shown that carriers of WFS1 heterozygosity have an increased risk of mood disorders, a finding later confirmed by additional studies." (PMID 39064493, 2024). "Currently, the patient is under the care of an otorhinolaryngologist, endocrinologist, ophthalmologist, and audiologist, as well as a psychologist, because mood disorders have been related to WFS1-associated diseases." (PMID 36330437, 2022). "The first round of literature search yielded over one hundred possible WFS1 mutations that were associated with mood disorder." (PMID 34746052, 2021). "Studies have shown that heterozygous carriers of WFS1 mutations (estimated to be 1% of US population) have a 26-fold increased risk of having a mood disorder." (PMID 34746052, 2021). "Based on these findings and our previous interest in the ER-stress-regulated pathways, we next analysed the TE-based regulation of the WFS1 gene, which is involved in neurodegenerative and mood disorders linked to endocrine pathologies and altered transcriptomic profiles." (PMID 34204806, 2021). "Heterozygous carriers of mutant WFS1, who are estimated to be as high as 1% of the general population, may also be at increased risk for mood disorders." (PMID 27434582, 2016). "It has been shown that mutations in the WFS1 gene make humans more susceptible to mood disorders." (PMID 23914152, 2013). "Therefore, it has been suggested that mutations in the WFS1 gene in humans play a marked role in the susceptibility to mood disorders." (PMID 23914152, 2013). "Among these were FKBP5 and WFS1, which have been previously implicated in mood disorders." (PMID 23945090, 2013).